APOD (apolipoprotein D)
Diseases named in the same sentence as APOD in open-access papers (continued):
Sharing a sentence is not in itself a finding about the gene and the disease.
Hepatic steatosis (5 papers, 2015 to 2024). Steatosis is a term used to denote lipid accumulation within hepatocytes. "Hepatic steatosis after human APOD overexpression in mice is due to an upregulation of PPARγ, leading to an increased formation of lipid droplets in hepatocytes." (PMID 34638803, 2021). "Experiments performed with HepG2 cells suggest that the hepatic steatosis is a result of an increased AA by apoD in the liver as confirmed by the enrichment of hepatic AA in H-apoD mice." (PMID 26083030, 2015). "Overexpressing H-apoD in HepG2 cells in the presence of AA strongly suggests that the presence of hepatic steatosis in Tg mice is the result of PPARγ activation by AA, one of the main ligand of apoD." (PMID 26083030, 2015). "Our study describes for the first time a role for apoD in the regulation of PPARγ and the downstream activation of metabolic pathways leading to hepatic steatosis." (PMID 26083030, 2015). "The hepatic steatosis can therefore be the result of increased apoD concentration in the liver or from the uptake of circulating apoD." (PMID 26083030, 2015). "We have been able to demonstrate that transgenic mice overexpressing the human ApoD will develop a non-inflammatory hepatic steatosis caused by an increase in fatty acid uptake due to increased hepatic CD36 expression, altered ARA metabolism, and amelioration of the ω-6/ω-3 ratio." (PMID 37237893, 2023). "Interestingly, an important characteristic of BPA-induced hepatic steatosis was that compared to the control group, the trend of APOD concentration in the serum of mice in the BPA group was opposite to the trend of the level of APOD protein expression in the liver." (PMID 37755785, 2023).
melanoma (5 papers, 2016 to 2025). A malignant, usually aggressive tumor composed of atypical, neoplastic melanocytes. "APOD (apolipoprotein D) and ABCA8 (ATP-binding cassette, sub-family A member 8) encode transporter proteins while PRAME (preferentially expressed antigen in melanoma) and CCL19 (chemokine ligand 19) genes are involved in immunoregulatory processes." (PMID 26961242, 2016). "However, APOD is high-expressed in other cancers such as melanoma and renal cell cancer." (PMID 35184747, 2022). "Among these, we detected co-upregulated melanoma marker gene MLANA and metabolic genes FASN, GPX3, and APOD, suggesting metabolic reprogramming as a key factor in invasiveness." (PMID 40866912, 2025).
mental disorder (5 papers, 2008 to 2021). A disease that has its basis in the disruption of mental process. "The Lipocalin Apolipoprotein D (ApoD) is one of the few genes consistently overexpressed in the aging brain, and in most neurodegenerative and psychiatric diseases." (PMID 32559215, 2020). "Apolipoprotein D (ApoD), a lipid binding protein of the Lipocalin family first known as part of bloodstream lipoprotein particles, is one of the few genes consistently over-expressed in the aging brain, and in all neurodegenerative and psychiatric diseases tested so far [reviewed in 18]." (PMID 28182653, 2017).
ovarian carcinoma (5 papers, 2020 to 2023). A malignant neoplasm originating from the surface ovarian epithelium. "Similarly, in the context of ovarian cancer, a separate study identified that genes associated with the pathogenesis of invasive cervical cancer, including the APOD genes, were downregulated in affected patients." (PMID 38067270, 2023). "Contrary to the role of APOD in ovarian cancer, the overexpression of APOE was found in the sera of ovarian cancer patients in comparison to healthy individuals; this overexpression was vital for the growth and survival of ovarian cancer." (PMID 38067270, 2023).
Stroke (5 papers, 2014 to 2025). Sudden impairment of blood flow to a part of the brain due to occlusion or rupture of an artery to the brain. "Our data suggest that the rs7659 SNP within the APOD gene could be associated with risk for stroke and stroke severity at stroke onset." (PMID 25261976, 2014). "In this first attempt to study if stroke repair mechanisms linked to certain regions within the APOD and SIGMAR1 genes may also affect recovery from stroke and severity of stroke, we performed a candidate gene study including twelve SNPs from these two genetic regions." (PMID 25261976, 2014). "Higher concentrations of ApoD have been detected in the brain’s white matter and peri-infarct regions after a stroke, suggesting that ApoD plays a role in transporting essential molecules such as cholesterol and phospholipids." (PMID 39767175, 2024). "Apolipoprotein D (Apo D) is a glycoprotein that assumes a role in numerous neurological disorders characterised by heightened oxidative stress, such as AD, stroke, and PD." (PMID 38344467, 2024). "The apolipoprotein D (APOD) has been suggested to be related to stroke not only by virtue of its ability to influence trafficking of lipids but also by modulating oxidative stress, synaptic plasticity and cell death." (PMID 25261976, 2014). "In animal models of stroke, increased APOD levels are correlated with better functional recovery, implying a possible function of APOD in the repair processes after stroke." (PMID 25261976, 2014). "We found that ApoD is upregulated in the ipsilateral cortex and hippocampus of old mice compared to the young ipsilateral cortex and hippocampus and the old contralateral cortex following stroke." (PMID 40661422, 2025). "Although rigorous statistical analysis did not provide clear evidence of an association between the APOD SNPs and stroke risk, severity or outcome, the possible genetic influence of polymorphism rs7659 is interesting and potentially relevant." (PMID 25261976, 2014). "With this background we aimed to investigate whether polymorphisms in the APOD and SIGMAR1 genes influence stroke severity as well as functional outcome in patients suffering from IS." (PMID 25261976, 2014). "Also, in experimental models of stroke and trauma, the levels of APOD are elevated." (PMID 25261976, 2014). "Among the SNPs analyzed, rs7659 within the APOD gene showed a possible association with stroke risk (OR = 1.12; 95% CI: 1.01-1.25; P = 0.029) and stroke severity (NIHSS ≥ 16) (OR = 0.70; 95% CI: 0.54-0.92; P = 0.009) when controlling for age, sex and vascular risk factors for stroke." (PMID 25261976, 2014).
demyelinating disease (4 papers, 2018 to 2025). A broad group of disorders that affect the myelin sheaths that cover the neurons. "The influence of both long-term and acute exposure of microglial cells to ApoD combined with relevant stimuli for aging, neurodegeneration or demyelinating diseases, reveal clear differences with ApoD roles in astrocytes, Schwann cells, neurons, and other cell types previously explored." (PMID 36779011, 2023).
diabetes (4 papers, 2014 to 2024). "The data allowed us to build models that could distinguish DKD from diabetes (AUC = 0.928) with 2 proteins (ALB, AFM), and distinguish DKD3 from DKD4 (AUC = 0.949) with 3 proteins (ANXA7, APOD, C9)." (PMID 34963468, 2021).
thyroid cancer (4 papers, 2022 to 2023). "While the association between APOD and thyroid cancer is understudied, one study found that APOD was downregulated in DTC." (PMID 38067270, 2023). "The expression level of APOD showed significant differences in the high- and low-risk groups of differentiated thyroid cancer recurrence." (PMID 37968615, 2023). "Here, we performed LASSO analysis and identified 6 critical fibroblasts related factors (PCOLCE2, APOD, APOE, TIMP1, HTRA3 and MT1A) and calculated the fibrosis scores based on their expression in patients with thyroid cancer." (PMID 36387901, 2022).
cyst (3 papers, 2020 to 2025). A sac-like closed membranous structure that may be empty or contain fluid or amorphous material. "ApoD is the primary cyst fluid component, and its plasma concentration in a mammary cyst patient is 1000 times higher than that in a healthy woman, which in turn indicates the role of apoD in BC carcinogenesis." (PMID 32306242, 2020).
encephalitis (3 papers, 2021 to 2023). An acute inflammatory process affecting the brain parenchyma. "Infection with the HCov-OC43 virus causes an increase in ApoD’s expression and a powerful and deadly encephalitis associated with an important inflammation in mice." (PMID 37237893, 2023). "In addition, it has been reported that apoD is upregulated in mice during acute encephalitis induced by the human coronavirus OC43 (HCoV-OC43) and produced T-cell infiltration into the brain, which is correlated to an increase in mouse survival rate." (PMID 34832544, 2021). "ApoD expression has been shown to be increased in the regenerated and remyelinating sciatic nerves, and in various injuries of the nervous system associated with stroke, entorhinal cortex lesion, traumatic brain injuries, coronavirus OC43 encephalitis and experimental kainic acid induced lesions." (PMID 37237893, 2023). "Of note, ApoD expression in the brain has been previously shown to be protective against human coronavirus OC43-induced encephalitis; however, the ability of ApoD to directly interact with the virus was not determined." (PMID 37343697, 2023).
hepatocellular carcinoma (3 papers, 2009 to 2023). A malignant tumor that arises from hepatocytes. "APOD may be a new tumor suppressor gene of hepatocellular carcinoma (HCC), and its expression status may be an available biomarker for predicting patient outcomes." (PMID 33505467, 2021).
neuroblastoma (3 papers, 2018 to 2023). Neuroblastoma (NB) is the most common solid, extracranial childhood tumor. "In 1321N1 astroglioma and SH-SY5Y neuroblastoma cells, it was found that ApoD derived from extracellular vesicles can be transferred from astrocytes to neurons, acting in a paracrine way to protect neurons from OS." (PMID 37237893, 2023).
amyloid (2 papers, 2022 to 2023). "Loss of ApoD increases the accumulation of hippocampal amyloid plaque, while overexpression of neuronal ApoD reduces hippocampal amyloid plaque." (PMID 36138870, 2022). "ApoD has been found to be strongly associated with deposits of amyloid in vessels but not with amyloid plaques in human brain tissue." (PMID 36138870, 2022). "In ApoD-null-APP-PS1 mice, models of amyloidogenic AD without ApoD expression, loss of ApoD increases the amyloid plaque load by almost two-fold, while overexpression of human ApoD (HApoD-APP-PS1 mice) decreases by 60% the amyloid-β 1-40 peptides and decreases by 34% the insoluble amyloid-β 1-42." (PMID 37237893, 2023).
anxiety disorder (2 papers, 2023 to 2024). A category of psychiatric disorders which are characterized by anxious feelings or fear often accompanied by physical symptoms associated with anxiety. "We investigated whether comorbid mood and anxiety disorders influence the effect of CI on plasma concentrations of HMGB1, RAGE, ROS/RNS, ApoD, and NRF2 in AUD patients." (PMID 38535924, 2024).
colon cancer (2 papers, 2020 to 2024). "APOD was shown to be a risk factor and substantially linked with lymphoid infiltration in a biologic information investigation on colon cancer (Liang, Su & Wu, 2021)." (PMID 38436027, 2024). "APOD was substantially expressed in the high-risk group, increased in colon cancer tissues, and had potential predictive value, according to a correlation study in the TCGA database against colon cancer (Liang, Su & Wu, 2021)." (PMID 38436027, 2024). "By studying colon cancer pathologic specimens, we confirmed that DYDC2, MS4A15, MAGEA1, WNT7A, APOD, and SERPINE1 were highly expressed in colon cancer tissues." (PMID 33680915, 2020).
demyelination (2 papers, 2010 to 2025). "A previous proteomics study showed increased levels of apolipoprotein D in patients with a clinically isolated syndrome of demyelination, indicating that abundance levels of this protein are highest in MScl patients at the time of their first exacerbation." (PMID 20805994, 2010).
depression (2 papers, 2020 to 2023). "Subsequently, APOD, PON1, BCHE, and IL6ST were reported to be related to depression, a finding consistent with our results." (PMID 33126421, 2020).
endometrial cancer (2 papers, 2023 to 2024). Primary or metastatic malignant neoplasm involving the endometrium (mucous membrane that lines the endometrial cavity). "For plasma proteins, a six-biomarker panel combining SERPINA4, APOA2, TTR, CRP, CLEC3B and APOD predicted advanced stage endometrial cancer with AUC 0.93 (0.85–0.99)." (PMID 38513301, 2024). "By contrast, a 3-marker panel of plasma proteins (APOD, PSMA7 and HPT) predicted endometrial cancer with an AUC of 0.87 (0.81–0.93), sensitivity of 75% (64%–86%), and specificity of 84% (75%–93%)." (PMID 38513301, 2024). "By contrast, a 3-marker panel of plasma proteins combining APOD, PSMA7 and HPT predicted endometrial cancer with an AUC of 0.87 (0.81–0.93), sensitivity of 75%, and specificity of 84%." (PMID 38513301, 2024). "For plasma proteins, a 4-marker panel combining CNDP1, CDC5L, APOD and PRDX6 had the least AIC value and predicted early-stage endometrial cancer with an AUC of 0.88 (0.82–0.95)." (PMID 38513301, 2024). "A 3-marker panel combining APOD, PSMA7 and HPT, predicted endometrial cancer with an AUC of 0.87 (0.81–0.93), sensitivity of 75% (64%–86%), specificity of 84% (75%–93%), and had the least AIC value." (PMID 38513301, 2024).
Fibroadenoma (2 papers, 2016 to 2020). A benign tumor of the breast characterized by the presence of stromal and epithelial elements. "Using machine learning to build predictive regression models, we selected a five-gene transcript set (ABCA8, APOD, CCL19, FN1, and PRAME) to discriminate between fibroadenomas and phyllodes tumors." (PMID 26961242, 2016).
gestational diabetes (2 papers, 2023 to 2025). Carbohydrate intolerance first diagnosed during pregnancy. "APOD levels are altered in pregnancy conditions including gestational weight gain, gestational diabetes, and placenta accreta." (PMID 40298034, 2025).
glaucoma (2 papers, 2016 to 2021). Increased pressure in the eyeball due to obstruction of the outflow of aqueous humor. "Within the African American cohort, APOA1, APOA2, APOA4, and APOD levels were significantly higher among glaucoma patients." (PMID 34602085, 2021). "Interestingly, Kliuchnikova and coworkers also identified cholesterol metabolism to be influenced during glaucoma, with apolipoprotein D down-regulated during pseudoexfoliation syndrome." (PMID 27788204, 2016).
lung carcinoma (2 papers, 2019). "The prognostic value related to the worse prognosis of IL-8, SCG2, NCAM1, CNTN1, CADM1, NPTX1, and APOD tumor transcripts were evaluated in seven lung cancer transcriptome datasets (validation set)." (PMID 31455042, 2019).
osteoporosis (2 papers, 2020 to 2023). A condition of reduced bone mass, with decreased cortical thickness and a decrease in the number and size of the trabeculae of cancellous bone (but normal chemical composition), resulting in increased fracture incidence. "It is worth noting that APOD plays an important role in the development of osteoporosis and the osteogenic differentiation of BMSC." (PMID 38283345, 2023).
pancreas carcinoma (2 papers, 2021 to 2024). "Among the top marker genes is apolipoprotein D (APOD) which was identified as a marker of juxtatumoral stromal cells in infiltrating pancreas carcinoma." (PMID 39112965, 2024).
periodontitis (2 papers, 2025). An acute or chronic inflammatory process that affects the tissues that surround and support the teeth. "Previous studies have determined that the APOD gene, which is highly expressed in periodontitis, inhibits FAO and concomitantly mitigates oxidative stress." (PMID 40606607, 2025). "Previous studies have reported heterogeneity in gingival fibroblasts in periodontal tissues, with four subsets significantly altered in periodontitis: Fib 1.1 (CXCL1, CXCL2, CXCL13); Fib 1.2 (APCDD1, IGFBP2, MRPS6); Fib 1.3 (APOD, GSN, CFD); and Fib 1.4 (TIMP3, ASPN, COL11A1)." (PMID 40801798, 2025).
prostatic intraepithelial neoplasia (2 papers, 2021 to 2025). "APOD was also found to be highly expressed in high-grade prostatic intraepithelial neoplasia and was identified as a potential biomarker." (PMID 40989158, 2025).
steatosis (2 papers, 2015 to 2021). Increased lipid within the cytoplasm of cells. "Another evidence that ApoD targets the skeletal muscles is that transgenic mice overexpressing hApoD in their CNS develop muscle steatosis." (PMID 33923459, 2021). "Taken together, our results demonstrate that the hepatic steatosis observed in apoD Tg mice is a consequence of increased PPARγ transcriptional activity by AA leading to increased fatty acid uptake by the liver." (PMID 26083030, 2015).
triple-negative breast carcinoma (2 papers, 2019 to 2023). An invasive breast carcinoma which is negative for expression of estrogen receptor (ER), progesterone receptor (PR), and human epidermal growth factor receptor 2 (HER2). "Adiponectin and apolipoprotein D were significantly elevated in triple-negative breast cancer (TNBC)." (PMID 37509426, 2023).
type 2 diabetes (2 papers, 2009 to 2021). "APOD gene polymorphisms were found in several populations, some of these variants being associated with a modified risk of Alzheimer’s disease or type 2 diabetes." (PMID 34638803, 2021). "In addition to its alteredexpression in the brain, apoD is upregulated in cultured myotubes from patientswith type 2 diabetes." (PMID 19946382, 2009).
viral infection (2 papers, 2022 to 2024). "Few studies have focused on the role of ApoD during virus infection so far." (PMID 38868762, 2024).
alcohol (1 paper, 2024). "The first-step variables introduced in the model were HMGB1, sRAGE, ROS/RNS, ApoD, NRF2, age of alcohol use onset, age of alcohol dependence onset, duration of alcohol use, duration of alcohol abstinence, and periods of alcohol abstinence." (PMID 38535924, 2024).
ankylosis (1 paper, 2013). Fixation and immobility of a joint. "In addition to Fgf23, R1MAb2 and vitamin D treatment similarly induced the expression of several genes, including osteocalcin (Ocn), osteoprotegerin (Opg), progressive ankylosis (Ank), dual-specificity phosphatase 6 (Dusp6), and apolipoprotein D (Apod)." (PMID 23451204, 2013).
appendicitis (1 paper, 2011). Acute inflammation of the vermiform appendix. "The protein abundance level of APOD in urine and its correlation with severity of appendicitis are validated by targeted mass spectrometry." (PMID 22194848, 2011).
asthma (1 paper, 2025). "Fibroblasts exhibited a relatively homogenous signature between healthy donors and donors with asthma except for the gene encoding apolipoprotein D (APOD; a protein that regulates lipid metabolism), which showed ~150% increased expression in fibroblasts from individuals with asthma." (PMID 40399607, 2025).
astroglioma (1 paper, 2023). "Interestingly, in SH-SY5Y neurons treated with PQ, the rescue in viability from addition of astroglioma-derived extracellular vesicles was similar to when purified ApoD was added, suggesting that ApoD is the main component of the extracellular vesicles responsible for the increase in viability." (PMID 37237893, 2023).
breast cyst (1 paper, 2025). A fluid-filled closed cavity or sac that is lined by an EPITHELIUM and found in the BREAST. "Elevated APOD expression is primarily observed in the glandular epithelium of the breast, with significant protein accumulation in the breast cysts." (PMID 41366282, 2025).
bronchiolitis (1 paper, 2019). Inflammation of the bronchioles characterized by swelling of the bronchioles and mucus accumulation. "The top gene in our bronchial epithelium analysis of percent emphysema was APOD (apolipoprotein D), a gene found differentially expressed in a study of emphysema severity and bronchiolitis." (PMID 30940135, 2019).